P2RX7 (purinergic receptor P2X 7)
Diseases named in the same sentence as P2RX7 in open-access papers (continued):
Sharing a sentence is not in itself a finding about the gene and the disease.
status epilepticus (24 papers, 2010 to 2025). Status epilepticus is defined as a continuous seizure lasting more than 30 min, or two or more seizures without full recovery of consciousness between any of them. "Elevated Ca2+ concentrations associated with status epilepticus block Sp1 binding to the microRNA-22 promotor, disinhibiting the suppression of P2rx7 mRNA translation into protein." (PMID 34144123, 2021). "Using the same intra-amygdala KA mouse model, P2X7R expression during status epilepticus also appears, however, to be controlled at the post-transcriptional level, involving the targeting of P2rx7 mRNA by microRNA-22, which is also under the control of Sp1." (PMID 34144123, 2021). "P2rx7 mRNA is elevated in the hippocampus following either intraperitoneal or intra-amygdala KA-induced status epilepticus in mice." (PMID 34144123, 2021). "Recently, we have reported that heat shock protein B1 (HSPB1) and purinergic receptor P2X7 (P2RX7) are involved in astroglial autophagy (clasmatodendrosis), following status epilepticus (SE)." (PMID 29749377, 2018). "By using a mouse model of unilateral status epilepticus and P2X7 receptor knockout (P2rx7−/−) mice, we demonstrate that the loss of the P2X7 receptor alters the expression of several miRNAs under normal physiological conditions and following status epilepticus." (PMID 32982684, 2020). "Western blotting confirmed the absence of the P2X7 receptor expression (~72 kDa) in the ipsilateral hippocampus of P2rx7−/− mice subjected to status epilepticus." (PMID 32982684, 2020). "An effect of reduced transcription was ruled out because P2rx7 mRNA levels showed minimal changes in the contralateral hippocampus after status epilepticus." (PMID 26631939, 2015).
Parkinson disease (22 papers, 2011 to 2025). A progressive degenerative disorder of the central nervous system characterized by loss of dopamine producing neurons in the substantia nigra and the presence of Lewy bodies in the substantia nigra and locus coeruleus. "Treatment with Brilliant Blue G, a P2RX7 antagonist, reduced parkinsonism symptoms and prevented dopaminergic neuron death." (PMID 37649719, 2023).
atherosclerosis (20 papers, 2009 to 2025). A disease characterized by the build-up of fatty material and calcium deposition in the arterial wall resulting in partial or complete occlusion of the arterial lumen. "P2RX7 is associated with several cardiovascular diseases, including hypertension, atherosclerosis, ischemia/reperfusion injury, and heart failure." (PMID 37180137, 2023). "Taken together, accumulated evidences have suggested that the P2RX7/NLRP3 signaling pathway may play a crucial role in the pathogenesis of both atherosclerosis and PD." (PMID 37649719, 2023). "In addition, P2RX7 knockout mice exhibit smaller atherosclerotic plaques than wild-type mice, further highlighting the potential therapeutic value of P2RX7-targeting strategies for preventing atherosclerosis progression." (PMID 37649719, 2023). "In the atherosclerosis dataset GSE28829, CD14 (AUC = 0.938), C1QB (AUC = 0.947), CD53 (AUC = 0.952), LY96 (AUC = 0.904), P2RX7 (AUC = 0.981), C3 (AUC = 0.817), and TNFSF13B (AUC = 0.875) demonstrated favorable diagnostic efficiency for differentiating patients with atherosclerosis from controls." (PMID 37649719, 2023).
osteoporosis (20 papers, 2012 to 2025). A condition of reduced bone mass, with decreased cortical thickness and a decrease in the number and size of the trabeculae of cancellous bone (but normal chemical composition), resulting in increased fracture incidence. "The observation that the anabolic stimulus of mechanical loading rescued the increased bone loss in the absence of P2X7R suggests a potential clinical intervention to help treat post-menopausal osteoporosis in women with loss of function P2RX7 polymorphisms." (PMID 29472582, 2018). "Recently, polymorphisms described in P2RX7 have been associated with osteoporosis in humans, which is typically linked with increased bone resorption and a decrease in bone mineral density (BMD)." (PMID 27193938, 2016). "Clinically, certain polymorphic variants of P2RX7 may identify patients, especially women, who are at greater risk of developing osteoporosis." (PMID 24934217, 2014). "As introduced above, the P2X7 receptor has a critical role in bone formation, metabolism and remodelling, leading to several genetic association studies of SNPs in the human P2RX7 gene with increased susceptibility to osteoporosis or risk of bone fracture." (PMID 25079442, 2014). "The purpose of this study was to determine whether genetic variation in the P2X7 receptor gene (P2RX7) is associated with decreased BMD and risk of osteoporosis in fracture patients." (PMID 22776862, 2013). "Global KO of P2rx7 significantly reduced bone mass in mice, while activating P2X7R alleviated osteoporosis, indicating that P2X7R participates in bone development and homeostasis." (PMID 40279432, 2025).
tuberculosis (20 papers, 2011 to 2026). A chronic, recurrent infection caused by the bacterium Mycobacterium tuberculosis. "Supporting the role of P2X7 signaling in controlling Tfh cell numbers in humans, tuberculosis patients carrying a single loss-of-function P2rx7 gene polymorphism produce more IgG against mycobacteria than control groups." (PMID 28859168, 2017). "Another meta-analysis addressed the role of P2RX7 SNP (rs1718119) with the odds of Tuberculosis and the findings indicate that this polymorphism could serve as a potential biological marker." (PMID 33467215, 2021). "First, we observed an increase in P2RX7 gene expression in the peripheral blood of tuberculosis patients compared to healthy donors." (PMID 34026666, 2021). "This view is supported by a recent study showing that P2RX7 expression in CD4+ T cells is particularly important for cell migration, proliferation and production of IFNγ in the pulmonary parenchyma during severe tuberculosis and influenza." (PMID 36993971, 2023).
bipolar disorder (19 papers, 2011 to 2025). A disorder of the brain that causes unusual shifts in mood, energy, activity levels and the ability to carry out day-to-day tasks. "We have previously shown this cognitive manic symptom factor to be associated with polymorphisms in the P2RX7 gene in bipolar disorder." (PMID 23861766, 2013). "This factor has been genetically associated with polymorphisms in the P2RX7 gene in bipolar disorder." (PMID 23861766, 2013). "Sleep deprivation increased P2RX7 expression in healthy persons and the putatively low-activity P2RX7 rs2230912 allele A variant was associated with rapid cycling in bipolar disorder." (PMID 22952630, 2012). "We found the putatively low-activity P2RX7 rs2230912 allele A variant to be associated with RC in bipolar disorder which supports earlier findings of P2RX7 associations to affective disorder." (PMID 22952630, 2012). "P2RX7 has previously been associated with bipolar disorder, depression, anxiety disorders, and cognitive symptoms in mania and is believed to play a role in antidepressant action and causation of bipolar disorder by influencing neurotransmission, neuroprotection, and neuroinflammatory responses." (PMID 22952630, 2012). "We hypothesized that P2RX7 expression in a healthy state is affected by disturbance in the circadian rhythm and further that polymorphisms in P2RX7 are associated with RC which is a subtype of bipolar disorder associated with a more vulnerable diurnal rhythm." (PMID 22952630, 2012). "Purinergic receptors, especially P2RX, are associated to the severity of symptoms in patients suffering from depressive and bipolar disorders, and genetic deletion or pharmacological blockade of P2RX7 induces antidepressant-like effect in preclinical models." (PMID 31656696, 2019). "P2RX7 is a candidate gene for bipolar disorder that was first identified by linkage analysis in a French-Canadian population." (PMID 22952630, 2012). "The link between P2RX7 SNPs and bipolar disorder remains unconfirmed." (PMID 41226305, 2025). "The study of P2RX7 expression was hypothesis-driven based on (i) previously reported P2RX7 genetic associations to bipolar disorder, and (ii) circadian rhythm disturbances reported in these patients and (iii) previous findings of mood dysregulation in mice lacking P2RX7 expression in the brain." (PMID 22952630, 2012).
colitis (18 papers, 2014 to 2025). Inflammation of the colon. "Consistent with the relevance of regulated P2X7R activity in Treg cells in intestinal homeostasis, purinergic antagonism or P2rx7 deletion rescued Treg cell numbers and, on the other hand, increased tumor incidence in a mouse model of colitis-associated colorectal cancer (CA-CRC)." (PMID 37762419, 2023). "Among the P2X and P2Y receptors, P2RX7 is the most studied in the induction of inflammatory responses and has been reported to participate in the development of colitis." (PMID 34354708, 2021). "P2rx7 deletion or pharmacological blockade led to clinical amelioration of IBD, reduced inflammation, and prevented disease onset in different murine models of colitis induced by dextran sulfate sodium (DSS) or 2,4,6-trinitrobenzene sulfonic acid (TNBS) administration." (PMID 37762419, 2023).
multiple sclerosis (18 papers, 2006 to 2025). A progressive autoimmune disorder affecting the central nervous system resulting in demyelination. "IL1B, P2RX7, IFNB1, IFNB1, TNF, and CASP1 enhance the network connectivity between multiple sclerosis (MS) complex genomes associated with COVID-19 and NOD-like receptor (NLR) signaling." (PMID 36483456, 2022).
Anxiety (17 papers, 2016 to 2026). Intense feelings of nervousness, tension, or panic often arise in response to interpersonal stresses. "Our study demonstrated that P2RX7 variants interact with distal and more etiological stressors in influencing the severity of anxiety symptoms, supporting previous scarce results and demonstrating its role in moderating the effects of stress." (PMID 37173368, 2023). "Thus, understanding the role of P2RX7 variation in anxiety also helps propose novel possible underlying pathways and mechanisms for the prevention and treatment of anxiety and anxiety disorders." (PMID 37173368, 2023). "Our present study investigated the effects of variation in the P2RX7 gene on anxiety in a large European general population sample, using a clumping procedure investigating all available SNPs along the gene." (PMID 37173368, 2023). "Ablation of P2RX7 not only alleviated muscle pathology but also results in improvements in cortex-mediated object recognition memory and in reduced anxiety-like behaviour in mdx (Dp427-null) mice." (PMID 34101068, 2022). "In animal studies, P2RX7 KO-mice produced a controversial relationship with anxiety-like behaviour, with no consensus on its role." (PMID 40429831, 2025). "We found no significant main effect, nor a significant interaction with recent negative life events for P2RX7 gene on current anxiety." (PMID 37173368, 2023).
Crohn disease (16 papers, 2008 to 2025). A gastrointestinal disorder characterized by chronic inflammation involving all layers of the intestinal wall, noncaseating granulomas affecting the intestinal wall and regional lymph nodes, and transmural fibrosis. "AZD9056, a P2RX7 inhibitor, demonstrated beneficial effects in a phase 2a clinical trial with moderate to severe Crohn’s disease." (PMID 37296626, 2023). "In patients with Crohn’s disease, P2RX7 expression is elevated in the colon." (PMID 37296626, 2023).
diabetic retinopathy (16 papers, 2017 to 2025). "Here, we show that the nucleoside reverse transcriptase inhibitor lamivudine (3TC), a newly discovered P2rx7 inhibitor, can attenuate progression of both neuronal and vascular pathology in diabetic retinopathy." (PMID 31035433, 2019).
Hypertension (16 papers, 2009 to 2025). The presence of chronic increased pressure in the systemic arterial system. "Among Chinese postmenopausal women, single-nucleotide polymorphism (rs3751143-C) of the P2RX7 gene was linked to a reduced risk of essential hypertension." (PMID 33995071, 2021). "It is also worth noting that SNPs for the P2RX7 gene played a role in hypertension but not in myocardial infraction." (PMID 33995071, 2021).
leukemia (16 papers, 2013 to 2025). A malignant (clonal) hematologic disorder, involving hematopoietic stem cells and characterized by the presence of primitive or atypical myeloid or lymphoid cells in the bone marrow and the blood. "In leukemia cells, P2RX7 inhibition markedly impairs energy metabolism, thereby suppressing cancer cell proliferation and invasion." (PMID 36803784, 2023). "Upregulation and activation of P2RX7 exhibit a pro-tumoral effect in various malignant tumors, such as leukemia, lung cancer, breast cancer, skin cancer, neuroblastoma, pancreatic ductal adenocarcinoma and esophageal squamous cell carcinoma." (PMID 36803784, 2023). "A range of leukaemias express P2RX7 mRNA, and higher positive rates and relative expression levels have been found in acute myeloid leukaemia (AML), acute lymphoblastic leukaemia, chronic myeloid leukaemia, and myelodysplastic syndrome patients compared to normal donor bone marrow mononuclear cells." (PMID 35897750, 2022). "In AML, P2RX7 mRNA levels varied between subtypes, with higher P2X7R expression in monoblastic and erythroid leukaemias compared to less differentiated leukaemias including acute promyelocytic leukaemia." (PMID 35897750, 2022).
COVID-19 (15 papers, 2021 to 2025). A disease caused by infection with severe acute respiratory syndrome coronavirus 2. "In contrast, our results revealed a significant association of the rs208294 SNP of P2RX7 with the severity of COVID-19." (PMID 38892324, 2024). "To fill this gap of knowledge, we now investigated if the rs2298383 SNP of ADORA2A, associated with decreased A2AR activity, and the rs208294 SNP of P2RX7, associated with increased P2X7R activity, were linked to the severity of COVID-19." (PMID 38892324, 2024).
mood disorder (15 papers, 2012 to 2025). A cognitive disorder a disturbance in which the person's mood is hypothesized to be the main underlying feature. "In the meta-analysis, we retrieved 10 studies that included data from 6,962 cases and 9,262 controls to evaluate the association between P2RX7 gene rs2230912 polymorphism and mood disorders." (PMID 24533115, 2014). "Future studies of large and clearly annotated samples are required to clarify or validate the association of these NS-SNPs in the P2RX7 gene with affective mood disorders." (PMID 25079442, 2014). "The aim of the present study is to perform a comprehensive meta-analysis to evaluate the association between P2RX7 gene rs2230912 polymorphism and mood disorders." (PMID 24533115, 2014). "Several groups have conducted genetic association analysis of SNPs in the P2RX7 gene in order to probe the role of the human P2X7 receptor in the pathogenesis of affective mood disorders." (PMID 25079442, 2014). "The P2RX7 gene has been identified as a locus of susceptibility to affective mood disorders." (PMID 25079442, 2014). "Further studies based on refined phenotypes may help to elucidate the association of P2RX7 gene rs2230912 polymorphism with mood disorders." (PMID 24533115, 2014). "Totally, 12 studies examined the association between P2RX7 gene polymorphisms and mood disorders." (PMID 24533115, 2014). "This suggests that similar P2RX7 variations in microglia may also alter cytokine release, potentially leading to neuroinflammation and impacting the functional state of neural networks, thereby increasing susceptibility to mood disorders." (PMID 40429831, 2025). "The P2RX7 gene was selected as a candidate gene in the first genetic studies of mood disorders based on the results of linkage studies and subsequent detailed studies of the 12q22–24 region." (PMID 24533115, 2014). "The P2RX7 gene, which encodes the P2X7 receptor, is located at chromosome 12q24.31 in humans, an important region for MDD, bipolar, and anxiety disorders, suggesting a genetic overlap in this group of mood disorders." (PMID 40429831, 2025). "However, in spite of the increased interest in purinergic signalling and especially P2RX7 in mood disorders, only a few studies focused on the role of variation in this gene." (PMID 34111150, 2021). "Overall, our meta-analysis suggests that P2RX7 gene rs2230912 polymorphism may not contribute to the risk of developing mood disorders using a case-control design." (PMID 24533115, 2014). "In the present study, we found no support for the specific hypothesis that P2RX7 gene rs2230912 polymorphism influences susceptibility to mood disorders in overall analysis and disease-specific analysis." (PMID 24533115, 2014).
asthma (14 papers, 2008 to 2025). "Taken together, these data suggest that of the P2X receptors, P2RX1, P2RX4, and P2RX7 are likely to be the most credible targets for respiratory diseases such as asthma." (PMID 35386996, 2021). "Notably, P2RX1, P2RX4, P2RX7, P2RY1, P2RY11, and P2RY14 were revealed as the most highly expressed purinergic receptors in lung tissue, therefore suggesting that these receptors have good potential as therapeutic targets for asthma and other respiratory diseases." (PMID 35386996, 2021).
Hyperglycemia (13 papers, 2015 to 2025). An increased concentration of glucose in the blood. "The results of our metabolic studies show that despite reduced systemic inflammation, P2rx7 deficiency does not alter diet-induced obesity, insulin resistance, and hyperglycemia associated with high-fat diet (HFD) feeding or thermogenic responses in BALB/c and C57BL/6 backgrounds." (PMID 33025427, 2020).
ischemic stroke (13 papers, 2014 to 2025). A stroke disorder caused by obstruction of blood flow to the brain, due to thrombotic (local blood clot formation) or embolic (due to a blood clot or other material traveling from another site) event. "Some studies have reported that the P2RX7/NLRP3 pathway caused neuronal pyroptosis after ischemic stroke in mice." (PMID 38965602, 2024). "Similarly, the implication of P2X7 receptor-mediated inflammation in atherothrombosis has prompted the study of SNPs in the human P2RX7 gene as a cardiovascular risk factor in patients with ischemic heart disease and ischemic stroke." (PMID 25079442, 2014).
pancreatic cancer (13 papers, 2012 to 2025). "Mechanistically, it has been shown that atorvastatin inhibits Akt signaling via the P2X7 receptor in human pancreatic cancer cells, and expression of Akt and the P2rx7 gene is also down-regulated in atorvastatin-fed Ptf1a-Cre; lox-stop-lox-KrasG12D/+ mice." (PMID 37958351, 2023). "Both in vitro and in vivo studies have shown that increased P2rx7 activity induces proliferation in GLC, LKM and pancreatic cancer (PCC), and its blockade reduces tumor burden in several cancer types and experimental models." (PMID 39859313, 2025).
colon carcinoma (12 papers, 2014 to 2025). "To verify that ATP release, which promotes P2RX7-mediated dendritic cell maturation, can enhance the therapeutic efficacy of chemotherapy by eliciting antitumor immunity, we subcutaneously inoculated BALB/c mice with syngeneic CT26 colon carcinoma cells." (PMID 38195677, 2024).
colorectal cancer (12 papers, 2015 to 2025). A primary or metastatic malignant neoplasm that affects the colon or rectum. "As for rs208294 SNP of P2RX7, differences were observed regarding cardiovascular conditions and colorectal cancer." (PMID 38892324, 2024). "The predicted mean cell count by the ERDCNN in the AKTP-P2rx7 group (24.26) was lower than that in the AKTP group (29.69), suggesting that P2rx7 over-expression induced the EMT phenotype in the malignant colorectal cancer organoids and the EMT phenotype inhibited the cell growth of those organoids." (PMID 31480740, 2019).